SHH (sonic hedgehog signaling molecule)
Diseases named in the same sentence as SHH in open-access papers (continued):
Sharing a sentence is not in itself a finding about the gene and the disease.
cancer (continued). "This review assesses the role of other signaling pathways implicated in SHH-MB and pathways which act synergistically with SHH signaling to promote tumorigenesis with other cancers; these latter pathways represent points for further investigation in the context of SHH-MB." (PMID 26512695, 2015). "Indeed the same study found that SHH-mediated migration is accomplished through leukotriene synthesis, suggesting a combination therapy target of both SHH and leukotriene synthesis pathways for cancer types." (PMID 26512695, 2015). "Whether HIF-1α regulates the biological behaviors of cancers via SHH signaling is a promising research direction." (PMID 25811359, 2015). "Towards exploring new venues of drug development for SHH signaling, this review will describe limitations with current therapies, pathways interacting with SHH signaling in MB, as well as pathways interacting with SHH in other cancer types." (PMID 26512695, 2015). "The SHH/Gli pathway is known to play a significant role in developmental and cancer biology." (PMID 26317547, 2015). "Numerous researches have shown that SHH production could be misregulated in various cancer types, notably those involving alteration of mesenchyme / stromal cells." (PMID 26694869, 2015). "However, few studies have been reported concerning the correlation between HIF-1α and the SHH pathway in human cancers." (PMID 25811359, 2015). "In agreement with this hypothesis, autocrine or paracrine expression of SHH has been extensively described in different human cancers." (PMID 23940460, 2013). "CCN1-induced activation of SHh signaling may be necessary for CCN1-dependent in vitro cancer cell migration and tumorigenicity of cancer stem cells in a xenograft in nude mice." (PMID 24287901, 2013). "We propose here that a drug interfering with the interaction between SHH and its dependence receptor CDON, such as the presented Fc-CDON3FbnIII, could be of potential benefit to the large number of patients suffering from cancers with high SHH levels." (PMID 23940460, 2013). "In addition, we have shown that these traits confer to the pair SHH/CDON a key regulatory role in cancer progression as recently shown for the dependence receptor DCC." (PMID 23940460, 2013). "Interestingly, recent evidence found that SHH was significantly upregulated in gemcitabine-resistant PC cells that simultaneously express cancer stem cell (CSCs) markers." (PMID 22900095, 2012). "Therefore, inhibition of angiogenesis via modulation of the SHH signaling pathway has become very attractive for cancer chemotherapy." (PMID 22949805, 2012). "SHH pathway is a morphogen required for proper pattern formation during embryogenesis; however, deregulation of this pathway is responsible for several human cancers." (PMID 22087285, 2011). "In several stem cells and cancer cells, SHH acts as a survival factor." (PMID 22087285, 2011). "Interestingly, almost all the widely-recognized hESC-associated pathways such as SHH, WNT, PRC2, Notch, PTEN and TGFβ have important linkage with cancer." (PMID 22041030, 2011). "Recently, Gli and Smo antagonists have been used to abrogate SHH signaling in human cancers." (PMID 22087285, 2011). "In addition, SHH plays an essential role in the development of cancers including PCa." (PMID 39881254, 2025).
cancer (continued). "The strong expression of SHH was observed in carcinoma cells of the G1 stage of ccRCC with a diffuse staining pattern (>50% of neoplastic cells), while SHH expression was mild in carcinoma cells of the G4 stage of ccRCC with less than 10% of stained carcinoma cells." (PMID 37240278, 2023). "Based on both the importance of the SHH signaling pathway in various cancers and the tumoroid characteristic of eutopic endometrial cells, we speculated that differential expression of key SHH signaling pathway proteins may change the biological behavior of eutopic endometrial cells." (PMID 35933378, 2022). "Importantly, treatment with an SHH inhibitor (RU-SKI 43) but not a NOTCH inhibitor (DAPT) reduced cell survival in NKX6-1-expressing cancer cells, indicating that an SHH inhibitor could be useful in treating LMS." (PMID 33906647, 2021). "Interestingly, activation of NTN1 expression in GBM could also be promoted by NF-κB, in an indirect manner since it has been reported that this transcription factor induces the expression of SHH in cancer." (PMID 34361013, 2021). "In addition to its biological importance, our study also suggested that preventing or inhibiting the exosomal transfer of SHH from CAFs to cancer cells may be a new strategy for the treatment of ESCC." (PMID 32030915, 2020). "Therefore, overexpression of SHH was expected in our cell lines and is lower in normal cells, hence SHH could act as a more specific and potent target for cancer therapeutics." (PMID 30899425, 2019). "Additionally, the cancer cells with Si‐EIF5A combined using recombinant sHH could inhibit the proliferation significantly (P < 0.05)." (PMID 30761741, 2019). "Additionally, 12 T cells also showed increased expression of the stemness genes Sox2, Oct4 and Nanog as well as several developmental genes known to be deregulated in cancer stem cells, such as SHH, Notch1, Gli1, and Jagged gene expression and protein expression." (PMID 26597727, 2015). "Furthermore, targeting the SHH pathway may have clinical implications for the improvement of cancer radiotherapy outcomes." (PMID 23762282, 2013). "Therefore, inhibition of angiogenesis via modulation of SHH signaling could be a promising strategy for anti-cancer drug development." (PMID 22949805, 2012). "Previous studies have shown that the SHH pathway, particularly GLI1, influences tumorigenesis in both cancer cells and cancer stem cells." (PMID 40894044, 2025). "A kind of hedgehog protein in EVs, sonic hedgehog (SHH), is revealed to promote HCC progression through the SHH pathway and facilitate the formation of cancer stem cells (CSCs)." (PMID 39227992, 2024). "Recent evidence suggests sulforaphane as a potent CSC inhibitor across multiple cancer types, as it targets crucial signaling pathways including WNT, Notch, SHH and NF-κB." (PMID 38455361, 2023). "In fact, the antidiabetic drug metformin has been investigated as an anti-cancer agent due to its ability to promote the activity of AMPK, suppress the action of mTOR, and subsequently attenuate SHH/GLI signaling." (PMID 37568705, 2023). "Expression of a receptor of the growth factor SHH, BOC showed a significant impact on survival for all cancers examined with expression above the cutoff in HNSCC and PDAC associated with better survival and worse survival in STAD." (PMID 37719704, 2023). "Moderate and strong immunoreactivity of SHH was mainly observed in the cytoplasm and extracellular matrix (ECM) of cancer tissues." (PMID 37964226, 2023). "The SHH pathway and its key transcription factor GLI1 play an essential role in cancer stemness-mediated tumorigenesis and multiple drug resistance in various cancers." (PMID 37149646, 2023). "Smoothened (SMO), which is essential to the sonic hedgehog homolog (SHH) signaling pathway, has been revealed to play a crucial role in the cellular behavior of cancer stem cells." (PMID 36865478, 2023).
cancer (continued). "Several reports found that the upstream and downstream expression of HH components, e.g., GLIs, SHH/IHH, SMO, PTCH1, and SUFU, are involved in the chemo/radioresistance of cancer cells." (PMID 37626893, 2023). "By characterizing the functional interaction between HHIP-AS1 and DYNC1I2 in cancer cells and in NSC, we unraveled the existence of an additonal layer whereby SHH signaling sustains cell growth and progression." (PMID 35831316, 2022). "Higher SHH and DHH expression also positively correlated with cancer invasiveness, lymph node metastases and recurrences." (PMID 36294994, 2022). "Similar observations have been reported for aberrant activation of SHH, the upstream BMP ligand, in cancers of the pancreas, stomach and colon." (PMID 35902550, 2022). "summarized the known target genes of GLI1 in human cancers, including components of the Hh signaling pathway (PTCH, SHH, and SMO)." (PMID 35785194, 2022). "One of key components in Hedgehog signaling, SHH is known to inhibit PTCH’s activity, by which activates cancer-related functions such as proliferation, apoptosis suppression and stem cell self-renewal." (PMID 35379174, 2022). "Anti-cancer effects involve many mechanisms, including oxidative stress, intrinsic and extrinsic mechanisms, as well as the survivin, PI3K/Akt/mTOR, SHH, Nrf2/Keap1, inflammation, and autophagy pathways." (PMID 34863080, 2021). "SIN inhibits proliferation, invasion, and migration and promotes apoptosis in cancer cells by modulating signaling pathways and microRNAs, such as PI3K/AKT/Wnt signaling pathway, SHh pathway, and miR-23a." (PMID 34179090, 2021). "One of the signaling pathways involved in cancer and specifically in the development of GBM is activated by the Sonic Hedgehog (SHH) molecule." (PMID 34361013, 2021). "The same study stated that high levels of SHH, PTCH1, and GLI2 are focally expressed in the epithelium of carcinoma in situ, suggesting potential early screening possibilities for unusual HH signaling activity." (PMID 33494284, 2021). "It has a well-recognized effect in suppressing the SHH pathway by inhibiting GLI proteins, a pathway related to human cancer pathogenesis." (PMID 32321992, 2020). "In addition, SHH produced by CAFs could regulate the microenvironment for cancer progression." (PMID 31979397, 2020). "Drug resistance develops following SHH/SMO/GLI signaling, upregulating drug-transport-pump expression in cancer stem cells." (PMID 32962123, 2020). "ED type that expressed SHH strongly induced CD11b/PTCH-double positive cells, which participate in cancer invasion around the front of cancer nests." (PMID 31744214, 2019). "Among the reasons for this is that the IL-6–STAT3 signaling axis in cancer cells activates NOTCH and SHH which in turn stabilize TWIST, SLUG and SNAIL by preventing their degradation." (PMID 29883385, 2018). "Efforts have been made to develop inhibitors of the SHh pathway, including Vismodegib, a Smo inhibitor, as well as GANT-61, a Gli inhibitor that regulates Gli-dependent transcription, to promote anti-cancer activity." (PMID 29416661, 2018). "Recently, FOXC1 has been shown to activate GLI2 in a SMO independent SHH pathway, which partly explains the aggressiveness of BLBC cell and adds a new role for FOXC1 in cancer cell stemness." (PMID 29487724, 2018). "Some of the players found to be affiliated with EMT and cancer stem-like cell maintenance include the PI3K/AKT pathway, RhoA, VEGFR, SOX2 and Wnt/β-catenin and SHH pathways." (PMID 29298329, 2018). "In conclusion, SHH inhibition can be an ideal opportunity to seize both mutagenic inflammation and CSC features to prevent cancer, simply achieving chemoquiescence." (PMID 26716648, 2016). "This cancer has at least four subgroups, including the WNT subgroups and the sonic hedgehog (SHH), plus the subgroups 3 and 4, with the molecular etiology remaining elusive for the latter two." (PMID 27843485, 2016).
cancer (continued). "Given the importance of GLI1/2 in the SHH pathway on promoting EMT and metastasis, blockade of GLI1/2 is a candidate for cancer treatment." (PMID 27043642, 2016). "The GABA-induced reduction in the expression of CD133, ALD-1, SHH, Gli-1 and SOX9 thus suggests significant inhibitory effects of GABA on cancer stem cells as contributing factors to the observed PDAC prevention in the current study." (PMID 27281617, 2016). "Compared to blocking the upstream regulators in the SHH pathway, an advantage of targeting GLI proteins is that these proteins serve as signaling hubs of multiple pathways that are activated in cancer cells, such as the TGF-β, WNT, and SHH pathways." (PMID 27043642, 2016). "The gene expression data are publicly available from the National Center for Biotechnology Information (NCBI), consisting of 73 individual cancer samples (8, 10, 16, and 39 samples for WNT, SHH, subgroup 3, and subgroup 4, resp)." (PMID 27843485, 2016). "According to Katoh’s summary, Wnt, FGF, Notch, SHH and TGFβ/BMP signaling cascades constitute the stem-cell signaling network, playing a key role in the maintenance or homeostasis of cancer stem cells." (PMID 25713298, 2015). "We next inquired if the SHH signaling pathway agonist, SAG, which acts by directly binding to downstream Smoothened, would promote cancer cell growth." (PMID 23762282, 2013). "Oct4 and Nanog are exclusively expressed in embryonic stem cells, Nestin is expressed in pluripotent neural stem cells, while KLF4, c-myc, and genes of Notch, SHH, and WNT pathways are expressed in TICs of a variety of cancers." (PMID 23185379, 2012). "However, they occurred independently of tissue invasion (perineural, lymphovascular, fat, bone, muscle, and mucous acini) and proteins related to the HH pathway (SHH, IHH, SMO, and GLI‐1), which contributed to the morphogenesis of this rare cancer." (PMID 40930949, 2025). "Even in tumors with elevated expressions of the HH target genes GLI1 and PTCH1, the expression of SHH, as a canonical driver of the HH pathway, is not necessarily high, suggesting other mechanisms of HH signaling activation in cancer." (PMID 40565349, 2025). "Increased SHH signaling in PDAC induces insulin-like growth factor 1 (IF1) expression and growth arrest-specific (GAS6) expression, leading to Akt signaling activation in cancer cells." (PMID 40136652, 2025). "Aberrant activation of the SHH pathway leads to the nuclear entry of the transcription factor GLI-1, where it binds to the promoter site of target genes, thereby enhancing the biological behaviors of cancer cells." (PMID 38730691, 2024). "In addition to its role in aggravating cancer, NF-κB activation induces a positive feedback loop within the TME through the upregulated expression of SHH." (PMID 38004606, 2023). "Inhibiting SHH and Gli1 signaling with a small molecule inhibitor in hepatic stellate cells that express high levels of SMO receptor and low levels of SHH ligands, in contrast to cancer cells, which express low levels of SMO and elevated SHH, inhibits proliferation in vivo." (PMID 37046676, 2023). "However, cancer stem cells (CSC) from different cells of origin have distinct cellular characteristics, including their dependence on SHH signaling." (PMID 36688010, 2022). "The low BMP secretion is most likely due to the absence of stimulating upstream ligands, such as SHH, which are normally secreted by cells in the microenvironment or by subsets of cancer cells." (PMID 35902550, 2022). "The SHH pathway inhibitor, CPM, has been used in the clinical treatment of cancer." (PMID 36262185, 2022). "Medulloblastoma (MB) is the most common malignant brain tumor in children, and recently the World Health Organization classified MB at the molecular level into four different types: MB WNT-activated, SHH-activated, group 3, and group 4." (PMID 36497448, 2022).
cancer (continued). "In summary, the SHH-signaling pathway appears to trigger both the origin of BE and its progression toward dysplasia and EAC, thus providing an attractive target for the prevention of both premalignant BE and full-blown esophageal malignancy." (PMID 33916875, 2021). "In addition to this canonical function, the SHH pathway cross talks with other tumorigenic pathways such as MAPK, mTOR, AKT, and PI3K, thus driving cancer progression." (PMID 34831357, 2021). "SHH and PI3K/AKT are both pathways that play important roles in cancer progression." (PMID 34956562, 2021). "Beyond the recently identified role played by MAML1 in SHh and YAP/TAZ signaling pathways, it is known that MAML1 can also functionally collaborate with different transcription factors involved in cell differentiation and cancer development." (PMID 33425921, 2020). "In light of significance of TGFβ1, SHH, EGFR, and LEF‐1 in the proliferation and migration of cancer cells, we examined the differential expression of those proteins in the cell lysis solution of NFs and CAFs and paid our attention to the different expression of SHH." (PMID 32030915, 2020). "Thus, the expression of SHH and GLI1 increased with the adenocarcinoma stages of cancer, suggesting a role of the Hh pathway in PCa proliferation." (PMID 32867229, 2020). "Among many pathways of cancer progression that PDAC relies on, anomalous activation of the sonic hedgehog (SHH) pathway has shown in a variety of human cancers, including, basal cell carcinoma, malignant gliomas, medulloblastoma, leukemias, and cancers of the breast, lung, pancreas, and prostate." (PMID 30899425, 2019). "Our results imply that SHH secreted from cancer cells facilitates cancer invasion not only by stimulating proliferation of cancer cells in an autocrine manner but also by promoting angiogenesis in a paracrine manner." (PMID 31744214, 2019). "SDF-1 expression was observed in the cancer parenchyma; however, SDF-1 was not expressed in the non-cancerous epithelium adjacent to the cancer parenchyma, similar to SHH expression." (PMID 31744214, 2019). "The SHH/GLI pathway is well known to play a significant role in developmental and cancer biology." (PMID 30899425, 2019). "Our data showed that both SHH and PTCH were expressed in the cancer parenchyma, thus suggesting that SHH signaling may operate in an autocrine manner in the cancer parenchyma." (PMID 31744214, 2019). "Due to the characteristic of each cell, this phenomenon (that uses different mechanisms of chemoresistance acquisition in cancer cells) is induced by signal transduction proteins such as Akt, mTOR, ERK, p38, SHH, and Wnt, depending on the activity or expression level of kinases." (PMID 31658599, 2019). "Among various factors, PDAC cells secrete Transforming growth factor beta-1 (TGF-β1), Fibroblast growth factor-2 (FGF2), sonic hedgehog (SHH) and platelet-derived growth factor (PDGF) that drive fibroblast proliferation and ECM deposition, which in turn, profoundly affect the cancer cell behavior." (PMID 30108679, 2018). "Targeting the stroma has gained interest with multiple preclinical and clinical trials targeting SHH, JAK2, and methods of either exploiting the secretory capability of CAFs to enhance drug delivery or inhibiting it to prevent its influence on cancer cell chemoresistance." (PMID 28351381, 2017). "Although TNF-α inhibition has been acknowledged as a potential strategy to prevent CAC, our study suggests that SHH inhibition to target IL-6 is another strategy to either prevent cancer or kill CSCs, which was never achieved before the current investigation." (PMID 26716648, 2016). "Several former researches showed that the Wnt, PI3K/AKT, and SHH/Gli1 pathways may be activated in CD44 positive and/or CD133 positive cancer cells." (PMID 26769843, 2016).